DHCR7 (7-dehydrocholesterol reductase)
Description:
Oxidoreductase that catalyzes the last step of the cholesterol synthesis pathway, which transforms cholesta-5,7-dien-3beta-ol (7-dehydrocholesterol,7-DHC) into cholesterol by reducing the C7-C8 double bond of its sterol core. Can also metabolize cholesta-5,7,24-trien-3beta-ol (7-dehydrodemosterol, 7-DHD) to desmosterol, which is then metabolized by the Delta(24)-sterol reductase (DHCR24) to cholesterol (By similarity). Modulates ferroptosis (a form of regulated cell death driven by iron-dependent lipid peroxidation) through the metabolic breakdown of the anti-ferroptotic metabolites 7-DHC and 7-DHD which, when accumulated, divert the propagation of peroxyl radical-mediated damage from phospholipid components to its sterol core, protecting plasma and mitochondrial membranes from phospholipid autoxidation. Component of the microsomal antiestrogen binding site (AEBS), a multiproteic complex at the ER membrane that consists of an association between cholestenol Delta-isomerase/EBP and DHCR7. This complex is responsible for cholesterol-5,6-epoxide hydrolase (ChEH) activity, which consists in the hydration of cholesterol-5,6-epoxides (5,6-EC) into cholestane-3beta,5alpha,6beta-triol (CT). The precise role of each component of this complex has not been described yet.
Synonyms: SLOS
Tractability: Small molecule: a high-quality ligand is known; it belongs to a druggable protein family. Antibody: UniProt predicts a signal peptide or a membrane-spanning region. PROTAC: ubiquitination databases record sites on it; its protein half-life has been measured; a small molecule that binds it is known.
Target class: Enzyme; Oxidoreductase
Gene: Protein-coding gene on chromosome 11 (71,428,193 to 71,452,868, reverse strand). Ensembl gene ENSG00000172893.
Subcellular location: Endoplasmic reticulum membrane
Subcellular location (Human Protein Atlas): Endoplasmic reticulum
Pathways (Reactome):
Metabolism: Activation of gene expression by SREBF (SREBP); Cholesterol biosynthesis from zymosterol (modified Kandutsch-Russell pathway); Cholesterol biosynthesis via desmosterol (Bloch pathway)
Gene Ontology:
Molecular function: 7-dehydrocholesterol reductase activity; cholesterol-5,6-oxide hydrolase activity; protein binding; NADP binding; oxidoreductase activity, acting on the CH-CH group of donors, NAD or NADP as acceptor
Biological process: cholesterol biosynthetic process; positive regulation of ferroptosis; sterol biosynthetic process
Cellular component: endoplasmic reticulum; membrane; nuclear outer membrane; endoplasmic reticulum membrane
Genetic constraint (gnomAD): Loss-of-function variants: 42 observed, 49.99 expected, observed/expected ratio (o/e) 0.84, 90% interval 0.65 to 1.09. The upper end of that interval is the gene's LOEUF score, 1.09, which puts it in group 4 of 6, group 1 being the genes least tolerant of losing a copy. Missense variants: 608 observed, 661.74 expected, observed/expected ratio (o/e) 0.92, 90% interval 0.86 to 0.98. Synonymous variants: 298 observed, 275.2 expected, observed/expected ratio (o/e) 1.08, 90% interval 0.98 to 1.19.
Gene-disease validity (ClinGen):
ClinGen rates the evidence that DHCR7 causes each of these diseases.
Smith-Lemli-Opitz syndrome (autosomal recessive): Definitive. Smith-Lemli-Opitz syndrome (SLOS) is characterized by multiple congenital anomalies, intellectual deficit, and behavioral problems.
Homologues: Orthologues: chimpanzee DHCR7 (99% identical), macaque DHCR7 (97% identical), pig DHCR7 (90% identical), dog DHCR7 (89% identical), mouse Dhcr7 (88% identical), rat Dhcr7 (87% identical), guinea pig DHCR7 (86% identical), tropical clawed frog dhcr7 (75% identical), zebrafish dhcr7 (73% identical), Caenorhabditis elegans dhcr-7 (23% identical), Drosophila melanogaster LBR (21% identical). Paralogues in human: TM7SF2 (34% identical), LBR (33% identical).
Diseases named in the same sentence as DHCR7 in open-access papers:
DHCR7 is named in the same sentence as 146 diseases in open-access papers, as found by Europe PMC text mining. Sharing a sentence is not in itself a finding about the gene and the disease. The quoted sentences say what the papers report.
Smith-Lemli-Opitz syndrome (73 papers, 2005 to 2025). "Smith-Lemli-Opitz syndrome is caused by 7-dehydrocholesterol reductase deficiency, leading to impaired cholesterol synthesis and accumulation of 7-dehydrocholesterol (7-DHC)." (PMID 41480351, 2025). "A carrier frequency of 2.4% was observed for Smith-Lemli-Opitz syndrome, caused by pathogenic variants in the DHCR7 gene." (PMID 41595422, 2025). "Smith-Lemli-Opitz syndrome is caused by mutations in DHCR7, leading to a reduction of cholesterol synthesis and a buildup of 7-dehydrocholesterol." (PMID 39456672, 2024). "Defective 3β-hydroxysterol-Δ7 -reductase (DHCR7) in the developmental disorder, Smith-Lemli-Opitz syndrome (SLOS), results in a deficiency in cholesterol and accumulation of its precursor, 7-dehydrocholesterol (7-DHC)." (PMID 36111785, 2022). "Mutation of 7-dehydrocholesterol reductase gene that encodes an enzyme involved in cholesterol metabolism, is the cause of Smith-Lemli-Opitz syndrome (SLOS), a DD with multiple congenital anomalies including cleft palate and holoprosencephaly." (PMID 35370658, 2022). "Smith-Lemli-Opitz syndrome (SLOS) is an autosomal recessive disorder caused by biallelic mutations in the DHCR7 gene, resulting in impaired biosynthesis of cholesterol." (PMID 34121999, 2021). "Located on chromosome 7, loss-of-function homozygous or compound heterozygous mutations in DHCR7 result in the Smith-Lemli-Opitz-Syndrome (SLOS, OMIM #270400), which is the most common cause of inborn errors of cholesterol synthesis." (PMID 33410752, 2021). "Smith-Lemli-Opitz Syndrome (SLOS) is a developmental disorder (OMIM #270400) caused by autosomal recessive mutations in the Dhcr7 gene, which encodes the enzyme 3β-hydroxysterol-Δ7 reductase." (PMID 33410752, 2021). "Reduced cholesterol levels occur in Smith-Lemli-Opitz syndrome which is caused by the decreased function of 7-dehydrocholesterol reductase, an enzyme catalyzing the last step of cholesterol synthesis." (PMID 32724221, 2020). "Smith-Lemli-Opitz syndrome (SLOS) is a rare genetic neurodevelopmental disorder caused by the defect in the 7-dehydrocholesterol reductase." (PMID 33115520, 2020). "Smith-Lemli-Opitz Syndrome (SLOS) is a recessive human disease caused by defective cholesterol (CHOL) synthesis at the level of DHCR7 (7-dehydrocholesterol reductase), which normally catalyzes the conversion of 7-dehydrocholesterol (7DHC) to CHOL." (PMID 29352199, 2018). "In the boy, Smith-Lemli-Opitz syndrome was also excluded by the study of DHCR7 gene, encoding for 7-dehydrocholesterol reductase." (PMID 27485500, 2016). "Genetic variation in DHCR7 appears to cause Smith-Lemli-Opitz syndrome, a clinical phenotype relating to cholesterol deficiency." (PMID 26305103, 2015). "Additionally, several de novo mutations in DHCR7 that lead to reduced DHCR7 expression during fetal development are responsible for Smith-Lemli-Opitz syndrome (SLOS), a rare inherited autosomal recessive disease." (PMID 40871701, 2025). "Similarly, mutations in DHCR7, a gene critical for the final step of cholesterol synthesis, cause Smith-Lemli-Opitz syndrome (SLOS), a neurodevelopmental disorder characterized by brain malformations and impaired neural differentiation." (PMID 40713855, 2025). "DHCR7 deficiency causes Smith-Lemli-Opitz syndrome (SLOS), which is an autosomal recessive syndrome charactered by multiple congenital abnormalities, including morphogenic, mental retardation and behavioral disorders, due to lack of cholesterol-derived steroid hormones." (PMID 36164611, 2022). "Given congenital deficiency of 7-dehydrocholesterol reductase results in Smith-Lemli-Opitz syndrome, our findings support the hypothesis that this commonly used medication may have previously unappreciated risks." (PMID 35379782, 2022). "Also, about 20% of patients with Smith-Lemli-Opitz syndrome, who are deficient in 7-dehydrocholesterol reductase (DHCR7), have cataracts." (PMID 34021134, 2021).
Smith-Lemli-Opitz syndrome (continued). "Diseases associated with DHCR7 include Smith-Lemli-Opitz Syndrome and holoprosencephaly." (PMID 33500538, 2021). "Similarly, DHCR7, the gene associated with the Smith-Lemli-Opitz syndrome, is somewhat above expectation in our analysis (p-value = 0.056) and healthy individuals were found to be homozygous carriers of putatively lethal disease alleles in other studies." (PMID 28957316, 2017). "Defects in DHCR7 gene were proven to be the cause of Smith-Lemli-Opitz syndrome, which may cause mental retardation, dysmorphism of the face, syndactyly, and holoprosencephaly as a result of insufficient sterol synthesis and 7-dehydrocholesterol accumulation." (PMID 29232835, 2017). "In man, defects in the DHCR7 enzyme underlie Smith-Lemli-Opitz syndrome (SLOS)." (PMID 24602487, 2014). "The clinical differentials of sex reversal with adrenal insufficiency include P450scc deficiency due to mutations in CYP11A1 gene, Smith-Lemli-Opitz syndrome (DHCR7 gene), NR5A1 (SF1) mutation-related sex reversal, CYP17 and 3-beta hydroxysteroid dehydrogenase deficiency (HSD3B2 gene)." (PMID 23748066, 2013). "Targeted disruption of the murine 3β-hydroxysterol-Δ7-reductase gene (Dhcr7), an animal model of Smith-Lemli-Opitz syndrome, leads to loss of cholesterol synthesis and neonatal death that can be partially rescued by transgenic replacement of DHCR7 expression in brain during embryogenesis." (PMID 17408495, 2007). "Smith-Lemli-Opitz syndrome (SLOS) is a rare genetic disorder caused by variants in the DHCR7 gene (OMIM:270400), which encodes 7-dehydrocholesterol reductase, the enzyme responsible for the final step of cholesterol biosynthesis." (PMID 40979443, 2025). "For instance, Smith-Lemli-Opitz syndrome (SLOS), caused by DHCR7 gene mutations impairing cholesterol synthesis, leads to accumulated 7-dehydrocholesterol (7-DHC) disrupting normal cholesterol function in tissues, ultimately causing ptosis." (PMID 41049435, 2025). "DHCR7 mutations in humans cause a clinical autosomal recessive genetic disease, namely Smith-Lemli-Opitz syndrome (SLOS), which is characterized with multiple abnormalities including growth deficiency, intellectual disability, and frequent infections." (PMID 39452933, 2024). "Mutations in DHCR7 cause Smith-Lemli-Opitz syndrome (SLOS), with cleft palate, postaxial polydactyly, 2–3 toe syndactyly, microcephaly, micrognathia, and intellectual disability as manifestations in humans." (PMID 38438535, 2024). "Similarly, patients with Smith-Lemli-Opitz syndrome, which results from mutations in the 7-dehydrocholesterol reductase (DHCR7) gene, and CDPX2, a result of mutations in the EBP gene, often present with normal cholesterol levels and elevated levels of sterol intermediates." (PMID 32430393, 2020). "Mutations in DHCR7 cause Smith-Lemli-Opitz syndrome (SLOS), which is characterized by cleft palate, postaxial polydactyly, 2-3 toe syndactyly, microcephaly, micrognathia, and mental retardation." (PMID 33256181, 2020). "Some mutations in DHCR7 lead to human autosomal recessive metabolic disorder, known as the Smith-Lemli-Opitz syndrome (SLOS)." (PMID 26751680, 2016). "Smith-Lemli-Opitz syndrome (SLOS) is an autosomal recessive disease caused by an inborn error of cholesterol metabolism due to the deficiency of the enzyme 7-dehydrocholesterol reductase." (PMID 25165593, 2014). "The best known is Smith-Lemli-Opitz Syndrome, in which patients have central nervous system (CNS) malformations, including holoprosencephaly and microcephaly, and skeletal defects (most often postaxial polydactyly) caused by mutations in 7-dehydrocholesterol reductase (DHCR7)." (PMID 21912524, 2011). "Smith-Lemli-Opitz syndrome (SLOS) is an autosomal recessive disorder of cholesterol biosynthesis caused by mutations in the gene encoding 7-dehydrocholesterol reductase (DHCR7) located on chromosome 11q12-13." (PMID 22937253, 2011).
Smith-Lemli-Opitz syndrome (continued). "Mutations that reduce the catalytic efficiency or even ablate DHCR7 lead to significant pathology in humans, known as Smith-Lemli-Opitz syndrome (SLOS)." (PMID 40118459, 2025). "Smith-Lemli-Opitz Syndrome (SLOS) is an autosomal recessive disorder of cholesterol biosynthesis caused by biallelic pathogenic variants in DHCR7, which encodes the enzyme 7-dehydrocholesterol reductase (DHCR7)." (PMID 40722188, 2025). "The newest clusters appear to have lighter colors, such as the 9th, 12th, and 13th, and they focus on (“COVID-19”, Coronavirus disease 2019), (“smith–”, Smith Lemli Opitz Syndrome), and (“7-dhc”, 7-Dehydrocholesterol Reductase), respectively." (PMID 36672957, 2023). "Smith-Lemli-Opitz syndrome (SLOS) is an autosomal recessive human disease caused by mutations in the gene encoding 7-dehydrocholesterol (7DHC) reductase (DHCR7), resulting in abnormal accumulation of 7DHC and reduced levels of cholesterol in bodily tissues and fluids." (PMID 30360379, 2018). "Smith Lemli Opitz syndrome (SLOS; OMIM #270400) is an autosomal recessive metabolic disorder caused by mutations in the DHCR7 gene." (PMID 26969503, 2016). "The Smith-Lemli-Opitz Syndrome (SLOS), a genetic condition of impaired cholesterol biosynthesis due to mutations of the 7-dehydrocholesterol reductase gene (DHCR7), has been found to be associated with autism, supporting genetic defects in cholesterol metabolism can cause autism." (PMID 24723866, 2014). "The best-characterized disorder of cholesterol biosynthesis is Smith-Lemli-Opitz syndrome, caused by mutations in DHCR7, which encodes the 7-dehydrocholesterol reductase that converts 7-dehydrocholesterol to cholesterol." (PMID 21912524, 2011). "Here, we report on a cohort of patients, whose physical findings and biochemical abnormalities in the neonatal period suggested a diagnosis of Smith-Lemli-Opitz syndrome (SLOS) (OMIM# 270400), a multiple congenital anomaly syndrome caused by biallelic DHCR7 variants affecting cholesterol metabolism." (PMID 39669238, 2023). "Finally, two mutant copies of the DHCR7 gene are either lethal (if sterol synthesis is fully eliminated) or result in a severe developmental disability called Smith-Lemli-Opitz syndrome (if some amount of residual cholesterol synthesis is preserved)." (PMID 36139049, 2022). "Elevated levels of 7-DHC are found in tissues and fluids of patients with the genetic disorder Smith-Lemli-Opitz syndrome (SLOS), which is caused by mutations in the gene encoding 7-dehydrocholesterol reductase (DHCR7)—the enzyme that converts 7-DHC to cholesterol." (PMID 35372835, 2020). "This association with dyslipidemia has not already been reported but, mutations in DHCR7 are associated with Smith-Lemli-Opitz Syndrome in which homozygous individuals present low serum cholesterol levels associated with other abnormalities." (PMID 24073860, 2013). "Smith-Lemli-Opitz syndrome (SLOS; OMIM 270400) is an autosomal recessive, multiple malformation, neurodevelopmental disorder caused by pathological variants of 7-dehydrocholesterol reductase (DHCR7), a terminal enzyme in cholesterol biosynthesis." (PMID 38236648, 2024). "Elevation of 7-DHC by genetic disruption of the DHCR7 gene leads to a severe intellectual and developmental disability known as Smith-Lemli-Opitz syndrome (SLOS)." (PMID 37759721, 2023). "We know that the developmental disorder known as Smith-Lemli-Opitz syndrome (SLOS), a condition arising from two mutant copies of the DHCR7 gene, is characterized by malformations in multiple organ systems." (PMID 36291744, 2022). "Smith-Lemli-Opitz syndrome (SLOS, OMIM #270400), an inborn error of cholesterol biosynthesis, is caused by reduced 7-dehydrocholesterol reductase (DHCR7) activity." (PMID 34439893, 2021). "Smith-Lemli-Opitz syndrome (SLOS) has effects all over the body due to a mutation in the DHCR7 gene, resulting in dysfunctional 7-dehydrocholesterol reductase." (PMID 31926618, 2020).
Smith-Lemli-Opitz syndrome (continued). "In the last fifty years, the discovery of a rare syndrome called Smith-Lemli-Opitz syndrome (SLOS, OMIM #270400) which is caused by mutations in the DHCR7 gene provided interesting information." (PMID 32911795, 2020). "Smith-Lemli-Opitz syndrome (SLOS) is a developmental disorder that affects many parts of the body, and is caused by a homozygous or compound heterozygous mutation in the gene encoding sterol delta-7-reductase (DHCR7) located on chromosome 11q13, with autosomal recessive inheritance." (PMID 29311971, 2017). "Yeast was also exploited as a model for Smith-Lemli-Opitz syndrome (SLOS), which occurs when the terminal enzyme of cholesterol biosynthesis, 7-dehydrocholesterol reductase (DHCR7), is defective." (PMID 38255855, 2024). "Examples of such congenital disorders and the affected enzymes include Smith-Lemli-Opitz syndrome (SLOS; DHCR7, OMIM# 270400), desmosterolosis (DHCR24, OMIM# 602398), lathosterolosis (sterol-C5-desaturase, OMIM# 607330), and mevalonate kinase (MVK, OMIM# 251170) deficiency." (PMID 33662384, 2021). "Smith-Lemli-Opitz syndrome (SLOS; OMIM #270400) is an autosomal recessive human disease caused by mutations in the DHCR7 gene, which encodes the enzyme 7-dehydrocholesterol reductase (DHCR7, EC1.3.1.21), the last enzyme in the cholesterol biosynthetic pathway." (PMID 24533230, 2013). "For instance, mutations in EVC and DHCR7 result in heart defects in humans (Ellis van Creveld Syndrome, OMIM 225500, Smith-Lemli-Opitz syndrome OMIM 270400) but not in the mouse." (PMID 23082118, 2012).